GSK3B (glycogen synthase kinase 3 beta)
Diseases named in the same sentence as GSK3B in open-access papers (continued):
Sharing a sentence is not in itself a finding about the gene and the disease.
Obesity (continued). "High levels of insulin-like growth factor 1 (IGF1) and insulin in obesity downregulate Glycogen synthase kinase 3 beta (GSK3B) activity by phosphorylating its serine residue, thereby altering the IL-17 signaling pathway, including upregulation of CXCL1, CCL20, and IL-6 expression." (PMID 37680632, 2023). "Overall, considering that obesity is usually accompanied by increased serum insulin levels, which are known to activate GSK3β, there is still a possibility that obesity can facilitate M2-like phenotype and thereby promote HCC progression in certain circumstances." (PMID 37266440, 2023). "Furthermore, obesity with prediabetes is associated with changes in IGF-1 signaling and acts on PI3K/Akt/GSK3β/β-catenin signaling, which results in rapid cell proliferation and development of breast tumors in obese rats than the lean rats." (PMID 37511200, 2023). "Littermate controls and conditional GSK-3β KO mice were subjected to an HFD to induce obesity." (PMID 35159367, 2022). "We previously reported dysregulated post‐exercise GSK3β signaling in adults with obesity which may suggest lower basal muscle glycogen content." (PMID 36541258, 2022). "We observed a differential effect of GSK-3β deletion on the β-catenin accumulation in developing vs. established obesity, which may account for the variable hypertrophic response." (PMID 32365965, 2020). "Moreover, when inhibiting Gsk3b activity, diet-induced obese mice significantly improved obesity symptoms, such as body weight gain, increased adiposity, dyslipidemia, and hepatic steatosis, due to the marked reduction of whole-body lipid content." (PMID 31801236, 2019). "Moreover, inactivation of GSK3β was shown to inhibit hepatocellular apoptosis in dietary obesity-promoted HCC22." (PMID 30523261, 2018). "Both aging and obesity reduced the phosphorylation of GSK-3β Ser9." (PMID 25257559, 2014). "Our results showed that decreasing p-GSK3β/GSK3β might benefit anti-obesity." (PMID 38641685, 2024). "However, its chronic inhibition may lead to increased body weight (obesity); therefore, strategies to maintain the body weight are critical to sustaining the metabolic benefit of GSK-3β inhibition." (PMID 35159367, 2022). "In addition, GSK-3β is critical to cardiac function in high-fat diet-induced obesity." (PMID 34349643, 2021). "Thus, obesity may attenuate depression treatment responses through induced inflammatory cytokines that alter Akt and GSK3β activity, resulting in changes in several key neurotransmitters." (PMID 26771598, 2016). "Anthocyanins, as natural bioactive compounds, hold significant promise in managing obesity and related metabolic disorders through their modulation of the PI3K/Akt signaling pathway and its downstream targets, such as GLUT4, FOXO, GSK3β, and mTOR." (PMID 40218884, 2025). "Taken together, ABS achieves an anti-obesity effect by improving lipid metabolism and mitochondrial function through the PI3K/Akt/GSK3β/β-catenin signaling pathway, and ABS are targeting the downstream of this signaling pathway c-Myc." (PMID 39594522, 2024). "The common targets of obesity, T2DM, and NAFLD are solute carrier family 6 member 4 (SLC6A4), acetylcholinesterase (ACHE), opioid receptor Mu 1 (OPRM1), and glycogen synthase kinase 3 beta (GSK3B)." (PMID 39575382, 2024). "Insulin-stimulated phosphorylations of INSR, IRS-1, Akt2, and GSK3β were markedly reduced in the liver of HFD-fed mice, indicating that HFD-induced obesity impaired hepatic insulin signaling." (PMID 35328400, 2022). "Through a network pharmacology analysis, the anti-obesity effect of hispidulin was predicted to act on estrogen, prolactin, Rap1, and PI3K-Akt signaling pathways by targeting AKT1, SRC, EGFR, and GSK3B." (PMID 34944408, 2021). "Previously, in the developing obesity model, we saw a reduction in cardiac GSK-3α activity (decreased GSK-3α phosphorylation) in HF-fed CM-GSK-3β KO hearts leading to an impairment in GSK-3-β-catenin degradation pathway and cardiac dysfunction." (PMID 32365965, 2020).
Obesity (continued). "The limitation of this study is that after obesity treatment by high-fat diet induction, BDNF activation and GSK3β inhibition were confirmed by endurance exercise and lithium treatment, but no direct change in brain function was confirmed." (PMID 32397675, 2020). "Based on the results of previous studies, endurance exercise and lithium treatments are expected to have a positive effect on obesity-induced neurodegenerative disorder prevention through BDNF activation and GSK3β inhibition in the hippocampus of obese rats." (PMID 32397675, 2020). "Overall this study demonstrates that early-onset obesity as a result of maternal HFD during lactation does not only dysregulate intrinsic-pulmonary STAT3-AMPKα-SOCS3, but also activate AKT/GSK3β pathway, indicative for insulin signaling." (PMID 27087690, 2016). "Aging and obesity significantly attenuated the phosphorylation of the insulin cascade kinases Akt (protein kinase B, PKB) and GSK-3β (glycogen synthase kinase 3β) in the hippocampi of the fa/fa rats." (PMID 25257559, 2014). "The most involved anti-obesity proteins include EGFR, STAT3, JUN, GSK3B, PPARG, and HSP90AA1." (PMID 38674532, 2024). "The network pharmacology highlighted this signaling pathway and our results indicate that ABS can upregulate the phosphorylation of PI3K, Akt, and GSK3β in the ABS treatment group compared to the model group, and this change is similar to other natural products improving obesity." (PMID 39594522, 2024). "Interestingly, the effect of GSK-3 isoform deletion on HFD-induced obesity was completely the opposite: GSK-3α KOs were protected; however, GSK-3β KOs on chronic HFDs gained more weight, thereby losing the protective effect on glucose tolerance." (PMID 35159367, 2022). "Interestingly, DSCR1 increases the expression of GSK3β in PC-12 cells and nuclear factor-κB-inducing kinase (NIK) induces hyperglycemia by phosphorylating CREB in obesity and DSCR1 stability." (PMID 30583978, 2019). "Additionally, previous studies have reported that obesity from a HFD decreases the activity of the hippocampal insulin signaling pathway, including the activity of IRS-1, PI3K, p-PDK1, p-AKT, and p-GSK-3β." (PMID 31311133, 2019). "The signalling molecules involved were reduced phosphorylation of GSK3β as well as downregulation of downstream genes of the NRF2 signalling pathway, including nicotinamide-adenine dinucleotide phosphate hydrogen quinone dehydrogenase 1 (NQO1) and HO-1 in high-fat diet fed obesity-prone rats." (PMID 38672518, 2024). "Wnt/GSK-3β pathway was considered to have negative effects on lipogenesis and obesity." (PMID 39170242, 2024). "The purpose of this study is to evaluate effects of obesity-induced neurodegenerative disorder prevention by analyzing the effects of long-term lithium and low intensity endurance exercise on the expression of BDNF and GSK3β in the hippocampus of high-fat diet-induced obese rats." (PMID 32397675, 2020). "In addition to TNF-α, other humoral agents associated with obesity might also be contributing to the activation of WNT signaling like IL-1β and adiponectin, which is decreased in the obese state and is not an inflammatory cytokine that can modulate GSK3β/β-Catenin signaling pathway." (PMID 32811441, 2020).
Hyperglycemia (52 papers, 2011 to 2026). An increased concentration of glucose in the blood. "Previous studies demonstrated that STZ-induced long-term (>40 days) hyperglycemia caused tau phosphorylation through activating glycogen synthase kinase 3 beta (GSK3β), due to the deficiency of insulin and subsequent inactivation of Akt in brain." (PMID 40054691, 2025). "The signaling cascade was further validated by examining the intermediary protein RISK pathway involving Akt/GSK-3β, which is closely associated with the adverse effects of hyperglycemia." (PMID 40737341, 2025). "GSK3β deactivation also counteracts the adverse pharmacological toxicity of hyperglycemia and insulin feedback caused by PI3K inhibition." (PMID 38755637, 2024). "GSK3β inhibitors have been associated with therapeutic benefits for a number of conditions associated with hyperglycaemia and dyslipidaemia." (PMID 27534430, 2016). "Selective loss of GSK-3β in skeletal muscle improves glucose tolerance and insulin signaling, while removal of this isoform in β-islet cells can reduce hyperglycaemia in diabetic IRS-2 KO mice." (PMID 21253590, 2011). "Moreover, our results also showed that glabridin alleviated hyperglycemia-induced bone loss and osteoblast cell apoptosis by modulating the expression of the Akt/NF-ĸB and Akt/GSK-3β pathways." (PMID 40243576, 2025). "Overall, the data support a model wherein hyperglycemia amplifies the activation of GSK3β in a REDD1-dependent manner, leading to canonical NF-κB signaling and an augmented renal immune response in diabetic nephropathy." (PMID 39880090, 2025). "In the context of biological insulin feedback derived from hyperglycemia, liver glycogen synthesis increases through elevated phosphorylation of GSK3β, contributing to the recovery of normal glycemic homeostasis." (PMID 38755637, 2024). "We find that muscle cells derived from MHS patients have increased content of an activated fragment of GSK3β — a specialized kinase that inhibits glycogen synthase, impairing glucose utilization and delineating a path to hyperglycemia." (PMID 36724092, 2023). "Hyperglycemia reduces the expression of genes that regulate hippocampal synaptic plasticity, including histone deacetylases and glycogen synthase kinase-3β (GSK3β), and neuronal long-term potentiation (LTP)." (PMID 37443762, 2023). "For instance, cell stressors like high glucose can activate autophagy through ERK activation, although hyperglycemia also inhibits it through mTORC1 activation and subsequent GSK3β inhibition." (PMID 35880011, 2022). "Then, we investigated several signaling kinases including AMPK, PKA, AKT and GSK3β that are known to mediate autophagy response, hyperglycemia-induced oxidative stress and/or apoptosis in diabetic kidneys." (PMID 33562139, 2021). "Changes in other genes associated with the Wnt canonical pathway have also been observed, including downregulation of Wnts, Fzds, β-catenin, Apc, and GSK-3β, suggesting regulation of Wnt expression by hyperglycemia in different embryonic tissues." (PMID 32434530, 2020). "The results obtained from HFD + low-dose STZ-induced diabetic mice and L6 cells showed that WS-PE exerted antidiabetic effects via the activation of Akt/GLUT4 and Akt/GSK3β and further improvement of hyperglycemia, IR, and dyslipidemia." (PMID 33061888, 2020). "Our results indicate that increased let-7b suppressing IGF1R activation ultimately leads to inactivation of Gsk3β and concurrent activation of glycogen synthase leading to hyperglycemia." (PMID 29069833, 2017). "Using the 30% total body surface area (TBSA) model of burn injury in rats we found that the miRNA let-7b can target IGF1R and downregulate its protein expression, in turn attenuating PI3K/Akt and Gsk3β activation leading to hyperglycemia." (PMID 29069833, 2017). "Our results show that the miRNA let-7b is robustly induced in burn injury and attenuates IGF1R protein expression and downstream activation of GSK3β that results in hyperglycemia." (PMID 29069833, 2017).
Hyperglycemia (continued). "The increased GSK3β phosphorylation in our study indicated that reduced hepatic glycogen synthase also contribute to the hyperglycemia." (PMID 25658428, 2015). "Hyperglycemia/oxidative stress stimulates the regulation of development and DNA damage 1 (REDD1), a stress-induced protein that promotes the association of PP2A and Akt, decreasing Akt phosphorylation and activity, and inhibiting GSK3b." (PMID 38256192, 2024). "Notably, GSK3β serves to inhibit glycogen synthesis, leading to reduced glycogenesis in the liver and muscles, thus contributing to hyperglycemia." (PMID 38274944, 2023). "Hence, in the present study, we aimed to analyze the possible role of antioxidant vitamins (C and E) in reducing the glyphosate-mediated development of hyperglycemia and hyperinsulinemia by downregulating the expression of GSK-3β and FOXO-1 mRNA in the liver." (PMID 38274944, 2023). "Of note, our recent data also demonstrated that GSK-3β was not inhibited in Pdx1+/−/APP/PS1 mice, indicating that GSK-3β is not closely linked to chronic hyperglycemia-induced tau hyperphosphorylation." (PMID 28467789, 2017). "However, it is unknown whether glyphosate can induce hyperglycemia by interfering with GSK-3β and FOXO-1, proteins involved in the regulation of glucose metabolism and insulin signaling in hepatocytes." (PMID 38274944, 2023). "Comparison of WT, Akita or placebo and/or tamoxifen treated Akita GSK3βfl/flCre+ mice demonstrated that neither the presence of the floxed allele nor cardiac specific deletion of GSK3β had an effect on the level of hyperglycemia and the decrease in body weight of Akita type 1 diabetic mice." (PMID 30978208, 2019). "Thus, increasing basal autophagy and AMPK activity by inhibiting GSK3β may be an effective strategy in the setting of hyperglycaemia and dyslipidaemia for restoring endothelial cell health and reducing atherogenesis." (PMID 27534430, 2016). "In a diabetic brain, hyperglycemia and central IR can synergize to disrupt the PI3K/AKT/GSK-3β pathway, thereby triggering excessive GSK-3β activation, leading to hyperphosphorylation of the tau protein." (PMID 41601904, 2026). "Anthocyanidins such as cyanidin-3-glucoside can ameliorate dyslipidemia, hyperglycemia and oxidative stress through the PI3K/Akt/GSK-3β pathway." (PMID 40440316, 2025). "Hyperglycemia/diabetes and sAD increase ACh esterase (AChE) activity and alter phosphatidylinositol-3 kinase (PI3K)/protein kinase B (Akt)/GSK3β-mediated signaling in the cerebral cortex." (PMID 37443762, 2023). "Genistein is capable of modulating hyperglycemia by activating the hepatic IRβ/PI3/AKT signaling pathway, increasing the phosphorylation of hepatic Foxo1/GSK3β and improving glucose metabolism of liver." (PMID 36570152, 2022). "Taken together, our results suggested that the protective effect of OB against contractile dysfunction induced by chronic hyperglycemia is, at least in part, due to its ability to rescue AMPK and GSK3β phosphorylation." (PMID 23066908, 2012). "In this condition, although the ability of insulin to phosphorylate Akt is reduced or absent, acute reduction of hyperglycemia can decrease elevated Akt-pSer473 and GSK3β-pSer9 in the hippocampus within minutes." (PMID 38416718, 2024). "In addition, it was shown that hyperglycemia increases PP2A activity, which dephosphorylates Akt and stimulates GSK3b." (PMID 38256192, 2024). "PI3K activation induces GSK3β inhibition via AKT, which activates NRF2 nucleus translocation, the expression of antioxidant enzymes and redox homeostasis regulation by counteracting the oxidative stress induced by hyperglycaemia in the retina." (PMID 31892189, 2019). "Thus, the unchanged OGTT, together with elevated PEPCK and GSK3β phosphorylation, suggests that HFHS dieting-induced hyperglycemia in the rats is most likely attributable to hepatic glucose production and not glucose utilization." (PMID 25658428, 2015).
Hyperglycemia (continued). "Experimental validation proved that mSMG ameliorated hyperglycemia, IR, and TNF-α, enhanced glucose consumption and glycogen synthesis, relieved the phosphorylation of JNK1 and IRS-2 (Ser388), and elevated the phosphorylation of Akt (Ser473) and GSK-3β (Ser9) and GLUT2 expression in KK-Ay mice." (PMID 39285464, 2024). "Therefore, we examined changes in AKT, GSK3β, NeuN, BDNF, and GFAP expression in a rat model, and our data showed that AKT and downstream GSK3β expression was reduced in the brains of rats with HFD/STZ-induced hyperglycemia." (PMID 38952685, 2024). "In this study, hyperglycemia increased BACE1 expression, Aβ deposition, tau protein phosphorylation, gliosis, and peripheral inflammation and decreased the levels of activated Akt and pS9-GSK3β (the inactive form of GSK3β) in 3×Tg-AD mice, whereas the AM404 treatment reversed these changes." (PMID 30426182, 2019). "By using human tau (441 a.a.)transgenic (hTau) mice, murine tau KO mice, and C57BL/6J (C57) mice, unexpectedly, we found that under acute hyperglycemia conditions, JNK but not previously reported GSK3β mediated tau phosphorylation." (PMID 40054691, 2025).